PSG5 (pregnancy specific beta-1-glycoprotein 5)
Synonyms: FL-NCA-3; PSG
Tractability: Antibody: UniProt places it where antibodies can reach, with high confidence; UniProt predicts a signal peptide or a membrane-spanning region; its Gene Ontology location is reachable by antibodies, with medium confidence.
Gene: Protein-coding gene on chromosome 19 (43,166,256 to 43,186,536, reverse strand). Ensembl gene ENSG00000204941.
Subcellular location: Secreted
Pathways (Reactome):
Hemostasis: Cell surface interactions at the vascular wall
Gene Ontology:
Molecular function: protein binding
Biological process: female pregnancy; heterophilic cell-cell adhesion; homophilic cell-cell adhesion
Cellular component: plasma membrane; extracellular region
Genetic constraint (gnomAD): Loss-of-function variants: 53 observed, 37.94 expected, observed/expected ratio (o/e) 1.4, 90% interval 1.12 to 1.75. The synonymous counts are far from expectation, so gnomAD's model fits this gene poorly and the ratio says little. Missense variants: 547 observed, 406.78 expected, observed/expected ratio (o/e) 1.34, 90% interval 1.25 to 1.44. Synonymous variants: 221 observed, 156.31 expected, observed/expected ratio (o/e) 1.41, 90% interval 1.27 to 1.58.
Homologues: Paralogues in human: PSG3 (89% identical), PSG7 (85% identical), PSG8 (85% identical), PSG6 (85% identical), PSG4 (85% identical), PSG1 (84% identical), PSG9 (82% identical), PSG2 (60% identical), PSG11 (59% identical), CEACAM1 (33% identical), CEACAM5 (33% identical), CEACAM6 (29% identical), and 12 more.
Diseases named in the same sentence as PSG5 in open-access papers:
PSG5 is named in the same sentence as 23 diseases in open-access papers, as found by Europe PMC text mining. Sharing a sentence is not in itself a finding about the gene and the disease. The quoted sentences say what the papers report.
breast carcinoma (3 papers, 2017 to 2024). "These include four loci that were associated (unadjusted P<0.05) with breast cancer (GTF2H2, ZNF385B, NAALADL2 and PSG5), and two loci associated with ovarian cancer (CYP2A7 and OR2A1)." (PMID 28145423, 2017). "Eight of these 29 (28%) CNV loci were confirmed by qPCR and/or Nanostring analysis, including four loci that were associated with breast cancer (GTF2H2, ZNF385B, NAALADL2 and PSG5) and two loci that were associated with ovarian cancer (CYP2A7 and OR2A1)." (PMID 28145423, 2017).
COVID-19 (2 papers, 2023 to 2024). A disease caused by infection with severe acute respiratory syndrome coronavirus 2. "In addition to these chromosomes, the causal SNPS of COVID-19 hospitalization on MM are also located in many regions of chromosome 19, involving genes such as PSG5, SLC22A31, FDX2, MAPT and others." (PMID 38400850, 2024).
laryngeal carcinoma (1 paper, 2024). Carcinoma that arises from the laryngeal epithelium. "The PSG5 gene, upregulated in PTCSUV-high regardless of tumor size, was previously reported as a prognostic marker for laryngeal cancer and is known to interact with prognostic lncRNAs in gastric cancer." (PMID 38745021, 2024).
cancer (9 papers, 2015 to 2025). A tumor composed of atypical neoplastic, often pleomorphic cells that invade other tissues. "Specifically, pregnancy-specific glycoproteins, including PSG4, PSG5, and PSG7, were those proteins jointly interacting with CTD-2218G20.2 and cancer-related proteins, which were highly correlated with CTD-2218G20.2 (PCC > 0.3)." (PMID 32117443, 2020). "We co-transfected kidney epithelial HEK293T cancer cells with GFP-PTEN and PSG5-PML/RARA constructs or with GFP-PTEN and PSG5 control plasmid." (PMID 27626703, 2016). "Specifically, CTD-2218G20.2 was predicted to interact with 86 proteins (Pearson correlation coefficient, PCC > 0.3), some of which, including PSG4, PSG5, and PSG7, could also interact with cancer-related proteins, including KISS1, TIMP2, MMP11, IGFBP1, EGFR, and CDKN1C." (PMID 32117443, 2020).
tumor (5 papers, 2011 to 2025). "On the other hand, variants associated with the PSG5, HLA-DRB5 and TMCO5A genes present an opposite trend, with a higher VAF in the primary tumor and lower in metastases." (PMID 39409151, 2024). "DEG analyses revealed the genes contributing to RFS and related to SUVmax (PSG5, TFF3, SOX2, SLC5A5, and SLC5A7) and tumor size (HOXD10, IFNA1, and FER1L6)." (PMID 38745021, 2024).
PSG5 also shares sentences with these, for which no sentence is quoted: preeclampsia (5 papers); cervical cancer (3); abortion (2); breast tumors (1); colorectal cancer (1); idiopathic pulmonary arterial hypertension (1); infection (1); kidney cancer (1); leukemia (1); Miscarriage (1); nephropathies (1); nephrotic syndrome (1); Obesity (1); osteoporosis (1); ovarian carcinoma (1); rheumatoid arthritis (1); Stillbirth (1); uterine cancer (1).